YTHDF2 (YTH N6-methyladenosine RNA binding protein F2)
Diseases named in the same sentence as YTHDF2 in open-access papers (continued):
Sharing a sentence is not in itself a finding about the gene and the disease.
lung cancer (46 papers, 2020 to 2025). A malignant neoplasm involving the lung. "The transcriptional repressor ZBTB4 and the tumor suppressor DAPK2 are negatively regulated by YTHDF2 and significantly associates with smoking-induced lung cancer." (PMID 36999016, 2023). "First, YTHDF2-deficient shYTHDF2-A549 lung cancer cells and control cells were subcutaneously injected into the bilateral axilla of six nude mice per group." (PMID 33980824, 2021). "In summary, we showed that YTHDF2 deficiency inhibited lung cancer cell proliferation and migration by modulating m6A levels of AXIN1, and impeding the activation of Wnt/β-catenin signaling." (PMID 33980824, 2021). "Both METTL14 and YTHDF2 exhibit low expression in lung cancer but are positively correlated with better patient prognosis, suggesting that impaired METTLE14-YTHDF2 activity contributes to the downregulation of KCTD10 in lung cancer." (PMID 40873559, 2025). "For example, in lung cancer, YTHDF2 promotes cancer progression and resistance to Erlotinib therapy through activating the Notch signaling pathway." (PMID 38351531, 2024). "For example, METTL3 is crucial for TGF-β-induced epithelial-mesenchymal transition in lung cancer cells, whereas YTHDF2 promotes lung cancer cell growth by enhancing the translation of 6PGD mRNA." (PMID 39138186, 2024). "Previous research has indicated that METTL14-binding peaks near the G6PD 3’-UTR regions can undergo methylation, thereby promoting translation facilitated by m6A ‘readers’ such as YTHDF2, which in turn enhances lung cancer cell growth." (PMID 39138186, 2024). "The expression of YTHDF1 and YTHDF2 is markedly upregulated in tumor tissues of lung cancer series and possesses tumor-promoting activities." (PMID 36999016, 2023). "On the other hand, hypoxia was reported to positively regulate the expression of YTHDF2 in lung cancer." (PMID 37012388, 2023). "As reported by Jin, YTHDF1 and YTHDF2 interacted competitively with YTHDF3 to module YAP expression in lung cancer in an m6A-independent manner." (PMID 36870954, 2023). "Lung cancer and gastric cancer each had a single gene (YTHDF2 and IGF2BP2, respectively) enriched in tumor cells." (PMID 35794212, 2022). "In two lung cancer cell lines, YTHDF2 knockdown inhibited proliferation but promoted migration, invasion, and the epithelial-mesenchymal transition." (PMID 35186724, 2022). "In conclusion, the function of YTHDF2 in lung cancer is controversial, and its specific role needs to be further clarified." (PMID 35382893, 2022). "The upregulation of an m6A reader, YTHDF2, was observed in lung cancer, which in turn promotes lung cancer by regulating the pentose phosphate (PPP) pathway." (PMID 34638933, 2021). "Based on this, the authors suggest that YTHDF2 can promote the growth of lung cancer by affecting the pentose phosphate pathway (PPP)." (PMID 33692959, 2021). "YTHDF2 promotes the proliferation of lung cancer cells and facilitates the pentose phosphate pathway (PPP) flux, which is critical in regulating cancer cell growth by supplying cells with ribose-5-phosphate and NADPH." (PMID 33928028, 2021). "Knockout of AXIN1 sufficiently rescued the inhibitory effect of YTHDF2 depletion on lung cancer cell proliferation, colony-formation, and migration." (PMID 33980824, 2021). "Subsequently, we validated that METTL3/YTHDF2 m6A axis also repressed KLF4 expression in lung cancer." (PMID 34774019, 2021). "YTHDF2 was also found to be upregulated in lung cancer tissues and promotes lung cancer cell growth." (PMID 34539889, 2021). "Taken together, these results demonstrated that the knockdown of YTHDF2 inhibited Wnt/β-catenin signaling and its downstream targets by upregulating AXIN1mRNA, thereby preventing the progression of malignant lung cancer cells." (PMID 33980824, 2021). "In lung cancer, YTHDF2 directly binds to the m6A modification site (3′-UTR) of glucose 6-phosphate dehydrogenase (6PGD) to promote the translation of 6-PGD and the proliferation of lung cancer cells." (PMID 33552994, 2020).
lung cancer (continued). "YTHDF2 was significantly upregulated in lung cancer, which could promote and enhance tumor growth by facilitating the 6GPD mRNA translation." (PMID 37047493, 2023). "However, ALKBH5 attenuates YTHDF2-mediated downregulation of oncogenic drivers such as SOX2, SMAD7, and MYC, contributing to the progression of aggressive lung cancer with KRAS mutation/LKB1 loss." (PMID 36999016, 2023). "For example, METTL3 was found essential for TGF-β-induced epithelial-mesenchymal transition of lung cancer cells; YTHDF2 could promote lung cancer cell growth via facilitating 6PGD mRNA translation." (PMID 34996469, 2022). "The results of studies on the role of YTHDF2 in lung cancer are complex." (PMID 35518355, 2022). "YTHDF1 and YTHDF2 may be new prognostic and drug targets related to lung cancer tumor immune microenvironment." (PMID 35069586, 2021). "YTHDF2 is up-regulated in lung cancer tissues and functions as an oncogene in lung cancer." (PMID 33928028, 2021). "YTHDF2 also has a certain regulatory effect in lung cancer and gastric cancer." (PMID 34187307, 2021). "In the field of lung cancer, the expression of YTHDF2 was aberrantly higher and facilitated the proliferation and growth of cancer cells, ribose-5-phosphate, and NADPH induced by pentose phosphate pathway might be the mechanism underlies." (PMID 34497675, 2021). "To date, the role of YTHDF2 in lung cancer (especially in LUAD) remains to be further explored." (PMID 34497675, 2021). "We found KLF4 expression were enhanced following METTL3 or YTHDF2 knockdown in lung cancer cells." (PMID 34774019, 2021). "In addition, YTHDF2 was found to be upregulated in lung cancer tissues, to promote cell growth in lung cancer, and to bind directly to the m6A-modified site in the 6-phosphogluconate dehydrogenase (6PGD) 3′ UTR." (PMID 32398132, 2020). "Moreover, YTHDF2 enhances the translation of 6-phosphogluconate dehydrogenase (6PGD) mRNA by binding to a given region in lung cancer cells." (PMID 32303268, 2020). "For instance, YTHDF2 interacts with the 3’-untranslated region (UTR) of 6-phosphogluconate dehydrogenase (6PGD) to enhance mRNA translation, thereby promoting lung cancer cell proliferation." (PMID 39138186, 2024). "This study revealed that m6A‐related genes significantly contribute to lung cancer, with the expression levels of YTHDF1, YTHDF2, ELAVL1 and ZC3H13 being crucial for predicting and treating lung cancer, providing new therapeutic targets." (PMID 39135292, 2024). "For example, YTHDF2 was upregulated and acted as an oncogene in multiple cancers, including acute myelocytic leukemia (AML), lung cancer, and gastric cancer." (PMID 35382893, 2022). "METTL3, RBM15, KIAA1429, YTHDF1, YTHDF2, HNRNPA2B1, HNRNPC, and IGF2BP1/2/3 expression levels in lung cancer tissues are significantly higher than those in normal tissues." (PMID 35518355, 2022). "Overexpression of YTHDF2 shortened the half-life of AXIN1 to decrease its expression to promote Wnt/β-catenin signaling, thus enhancing the progression of lung cancer." (PMID 35382893, 2022). "As expected, Knockdown of YTHDF2 increased the mRNA and protein levels of AXIN1 in A549 and H1792 lung cancer cells; whereas, the overexpression of YTHDF2 decreased the protein AXIN1 in A549 and H1792 cells." (PMID 33980824, 2021). "In our present study, we showed that YTHDF2 expression was abnormally up-regulated in LUAD, and that YTHDF2 was crucial for lung cancer cell tumorigenesis and metastasis." (PMID 33980824, 2021). "YTHDF2 binds to the m6A modification site of 6-phosphogluconate dehydrogenase (6PGD) 3’-UTR and facilitate 6PGD mRNA translation in lung cancer cells." (PMID 33692959, 2021). "In lung cancer, YTH domain family 2 (YTHDF2) promotes 6PGD mRNA translation by directly binding to the m6A modification site, leading to increased oxidative PPP flux." (PMID 32582032, 2020).
lung cancer (continued). "For instance, in lung cancer cells, the m6A methyltransferase methyltransferase-like 3 (METTL3) catalyzes the m6A modification of FSP1 mRNA, which is subsequently recognized by the m6A reader protein YTH Domain Family Member 2 (YTHDF2)." (PMID 40862825, 2025). "The results revealed that patients with lower YTHDF2 expression had shorter overall survival (OS) times, and this trend was not as apparent in other lung cancer types, such as small cell lung cancer or squamous cell lung cancer." (PMID 35186724, 2022). "Interestingly, the elevated expression of YTHDF2 was positively correlated with the OS and RFS of lung cancer patients, which was attributed to YTHDF2 promoting the enrichment of tumor-infiltrating lymphocytes and inhibiting the expression of PD-L1." (PMID 35382893, 2022). "Moreover, the upregulation of YTHDF2 significantly increased the proliferation, migration, colony formation, metabolic defects, and pentose phosphate pathway (PPP) flux of lung cancer cells to promote lung cancer growth." (PMID 35382893, 2022). "Furthermore, m6A regulators play an important role in lung cancer progression, for example FTOH and ALKBH5 have been shown to promote the proliferation of lung cancer cells, and YTHDF2 can regulate tumor metabolism." (PMID 34805165, 2021). "While YTHDF1 and YTHDF2 expression promote pancreatic and lung cancer cell proliferation, no equivalent research has to date determined a causal relationship between YTHDF1 or YTHDF2 expression in gliomagenesis." (PMID 32375856, 2020). "In lung cancer, YTHDF2 depletion could increase lactate production, and decrease oxidative PPP flux and NADPH/NADP+ ratio, indicating that YTHDF2 participated in lung cancer cells metabolism and affected tumor cells growth." (PMID 32276589, 2020). "Elevated levels of YTHDF1 and YTHDF2 correlate with a good survival outlook, more tumour‐infiltrating lymphocytes and PD‐L1 down‐regulation in NSCLC patients, suggesting their potential as prognostic markers and therapeutic targets related to the TIME in lung cancer." (PMID 39135292, 2024). "The two studies also showed YTHDF2 could recognize m6A-modified sites of lncRNA KCNQ1OT1 or PVT1 and regulate their stability, but whether ALKBH5 regulates the stability of PVT1 via YTHDF2 in lung cancer cells remains to be examined further." (PMID 36376862, 2022). "YTHDF2 inhibits the migration and invasion of lung adenocarcinoma cells by regulating the FAM83D-TGFβ1-pSMAD2/3 pathway, which may play an important role in lung cancer metastasis." (PMID 35186724, 2022). "As previous research showed that in bladder cancer METTL3/YTHDF2 m6A axis accelerates carcinogenesis by degrading transcription factor KLF4, we also examined whether METTL3/YTHDF2 m6A axis inhibited KLF4 expression in lung cancer." (PMID 34774019, 2021).
ocular melanoma (44 papers, 2019 to 2025). A melanoma that arises from the structures of the eye or ocular adnexa. "Histone lactylation promotes oncogenesis by enhancing the expression of m6A reader YTHDF2 in ocular melanoma." (PMID 40612514, 2025). "YTHDF2 is proposed as a possible therapeutic target, with implications for controlling ocular melanoma via altering the lactylation of histones." (PMID 39968078, 2025). "The study, titled “Histone lactylation drives oncogenesis by facilitating m6A reader protein YTHDF2 expression in ocular melanoma” (n=38.3), has garnered significant attention in the research community." (PMID 40672754, 2025). "Lactylation signals are concentrated in the YTHDF2 promoter region in ocular melanoma, which has been found to function as an oncogene in a variety of tumors." (PMID 39968078, 2025). "Histone lactylation was found to drive oncogenesis by facilitating YTHDF2 expression in ocular melanoma." (PMID 38297099, 2024). "A poor prognosis for patients with ocular melanoma can result from elevated lactylation levels in tumor tissue because these lactylation levels promote the production of YTHDF2, which promotes oncogenesis." (PMID 38983918, 2024). "Histone lactylation promotes oncogenesis by facilitating the expression of YTHDF2 in ocular melanoma." (PMID 38516932, 2024). "The YTHDF2 (YTH N6-methyladenosine RNA binding protein 2) promoter region was shown to have increased lactylation signals in ocular melanoma." (PMID 38983918, 2024). "In ocular melanoma cells, L-lactylation of histone H3 in the promoter region of the YTHDF2 gene induces the expression of YTHDF2, an N6-methyladenosine (m6A) reader protein." (PMID 39438765, 2024). "Elevated levels of lactylation in tumour tissue can lead to a poor prognosis for ocular melanoma by facilitating YTHDF2 expression, which drives oncogenesis." (PMID 37060186, 2023). "H3K18la can also modulate the expression of YTHDF2 to participate in the progression of ocular melanoma." (PMID 37684641, 2023). "Genetically or pharmacologically impairing this histone lactylation of YTHDF2 not only inhibit proliferation and migration in vitro, but also reduces tumor size of orthotopic xenografts of ocular melanoma, reflecting the relevance of this modification in vivo." (PMID 36226054, 2022). "Since YTHDF2 can be directly regulated by H3K18la, we next explored its function in ocular melanoma." (PMID 33726814, 2021).
ocular melanoma (continued). "After overexpressing YTHDF2 in ocular melanoma cells, the anticancer effects of glycolysis inhibitors were partially compromised, including cell growth, colony formation and migration." (PMID 33726814, 2021). "First, we found that YTHDF2 was highly expressed in ocular melanoma cell lines at both the RNA and protein levels (lanes 2–9)." (PMID 33726814, 2021). "We then verified the function of YTHDF2 in ocular melanoma cells by silencing its expression with three short hairpin RNAs (referred as shYTHDF2-1, shYTHDF2-2 and shYTHDF2-3)." (PMID 33726814, 2021). "In summary, our study initially revealed histone lactylation accelerate tumorigenesis through activating m6A reader protein, YTHDF2, and thereby provide novel histone lactylation targets for treating ocular melanoma." (PMID 33726814, 2021). "In addition, expression of YTH N6-methyladenosine RNA Binding Protein F2 (YTHDF2) was facilitated by histone lactylation to drive oncogenesis in ocular melanomas." (PMID 39742570, 2025). "In ocular melanoma cells, elevated histone lactylation could promote the transcription of YTH N6-methyladenosine RNA binding protein F2 (YTHDF2)." (PMID 38993478, 2024). "In ocular melanoma, lactylation signals were also found to be significantly enriched in the YTHDF2 (YTH N6‐methyladenosine RNA binding protein 2) promoter region and YTHDF2, one of the m6A code readers, has been reported to function as an oncogene in a variety of tumours." (PMID 37060186, 2023). "In ocular melanoma, histone lactylation could promote cancer process by enhancing the expression of YTHDF2." (PMID 37945340, 2023). "In addition, there are reports that p300 can serve as a “writer” of lactylation on the YTHDF2 promoter in ocular melanoma cells." (PMID 36050306, 2022). "YTHDF2, a reader of m6A, plays a vital role in promoting tumorigenesis in ocular melanoma." (PMID 36050306, 2022). "Notably, we found that YTHDF2 expression was positively correlated with global histone lactylation levels (R = 0.475, P < 0.001) and H3K18la levels (R = 0.393, P < 0.001) in ocular melanoma cohort." (PMID 33726814, 2021). "Taken together, these data indicated that YTHDF2 acts as an oncogene in ocular melanoma." (PMID 33726814, 2021). "In addition, overexpression of YTHDF2 in ocular melanoma cells accelerated tumorigenesis, which further indicates the oncogenic gain of function of YTHDF2." (PMID 33726814, 2021). "Further study could concentrate on the oncogenic role of other readers, such as YTHDF2/3, in regulating tumor formation of ocular melanoma." (PMID 31722709, 2019). "Additionally, YTHDF2 acts as an oncogenic factor in ocular melanoma." (PMID 40483535, 2025). "Additionally, lactylation drives oncogenesis by facilitating YTHDF2 expression in ocular melanomas." (PMID 37391814, 2023). "In addition, immunofluorescence staining showed that YTHDF2 expression was significantly upregulated in ocular melanoma tissues compared to normal melanocyte tissues (p < 0.05) and that higher expression of YTHDF2 was positively correlated with a poor prognosis (log-rank test, p < 0.05)." (PMID 33726814, 2021). "The lactylation of H3K18 promotes the transcription of YTH N6-methyladenosine RNA-binding protein 2 (YTHDF2), which is involved in ocular melanoma." (PMID 38918851, 2024).